CAV1 (caveolin 1)
Diseases named in the same sentence as CAV1 in open-access papers (continued):
Sharing a sentence is not in itself a finding about the gene and the disease.
Stroke (continued). "However, the relationship between Cav‐1 levels and sICH remains largely unknown in stroke patients treated with EVT." (PMID 38757755, 2024). "Caveolin-1 may play an important role in protecting the brain from stroke." (PMID 36289917, 2022). "Therapeutic approaches targeting Cav-1 may provide new opportunities for improving stroke outcome." (PMID 32523952, 2020). "Indeed, understanding Cav-1 changes after stroke may lead to new treatment options for improving outcome after stroke." (PMID 32523952, 2020). "Therefore, lower perivascular AQP4 after stroke in cav-1 KO mice could be a consequence of decreased laminin." (PMID 32523952, 2020). "In addition, we discussed evidence that cav-1 may serve to promote neuroprotection after stroke and also listed some opposing results." (PMID 30572925, 2018). "Thus, Cav-1 could be developed into a novel therapeutic target protein for promoting neurogenesis for the treatment of stroke and neurodegenerative diseases in the future." (PMID 21826216, 2011). "In summary, Cav-1 and autophagy form a tightly interconnected regulatory axis that critically governs BBB integrity and neurovascular function in stroke through their bidirectional interaction and modulation of TJPs." (PMID 41030451, 2025). "We compared the efficacy of the three treatment outcomes by analyzing the National Institutes of Health Stroke Scale (NIHSS) scores, and the levels of serum inflammatory factors (IL-8, TNF-α, and IL-1β), cone like protein-1 (VILIP-1), and caveolin-1 (Cav-1)." (PMID 38827855, 2024). "We also found that Storax has effects in decreasing the expression of Cav-1 and AQP4 and increasing the expression of Mfsd2a and PDGFR-β at 6 h after stroke." (PMID 35873558, 2022). "The work indicates a link between Cav-1, reactive astrocyte morphology and perivascular astrocytic AQP4 expression, brain edema and consequent recovery after stroke." (PMID 32523952, 2020). "Increased Glut1 expression confirmed induction of OGD, whereas vesicle markers Cav1 and Plvap were reduced at the RNA level upon OGD, potentially a compensatory regulation to the increased protein levels as observed previously in vivo in stroke." (PMID 35752654, 2022). "Lower perivascular AQP4 expression was observed after stroke in absence of Cav-1, suggesting a role for Cav-1 in AQP4 expression in astrocyte perivascular end-feet." (PMID 32523952, 2020). "As observed for AQP4-labeling, there was no change in the length of GFAP-positive branches in Cav-1 KO stroke mice compared to sham." (PMID 32523952, 2020). "Caveolin-1 also modulates the blood-brain barrier (BBB) permeability, pro-survival signaling, angiogenesis, neuroinflammation, and ischemic preconditioning, which are critical processes during stroke development." (PMID 32257548, 2020). "Furthermore, miR-124 attenuated apoptosis by regulating the Cav-1/PI3K/Akt/GSK3β pathway in Alzheimer's disease 121, and promoted stroke-induced neuroplasticity by targeting the Notch signaling pathway." (PMID 31673241, 2019). "Our data demonstrate that Rab7a-mediated rescue of acute BBB dysfunction after stroke in vivo is not accompanied by changes in Caveolin-1 protein levels or transcellular permeability in vivo, although the inflammatory milieu in stroke increases Cav-1 protein levels in BECs." (PMID 41024170, 2025). "Observational studies focusing on elderly without stroke and interventional studies in animals (such as gene knockout studies) are needed to determine whether Cav-1 is really a marker of CMBs and a potential target for treating cerebral small vessel disease." (PMID 27119011, 2016). "We show now that mice lacking Cav-1 have significantly less astrocytic AQP4 in the lesion core, perilesion and contralateral cortex after stroke." (PMID 32523952, 2020). "AQP4-labeling was absent in the striatum of Cav-1 KO mice at six but not in WTs, indicating a difference in AQP4 expression after stroke." (PMID 32523952, 2020).
glioblastoma (41 papers, 2008 to 2025). The most malignant astrocytic tumor (WHO grade IV). "Pharmacologically blocking CAV1 restores the function of the tumor-associated macrophage and facilitates more successful immunotherapeutic strategies directed against glioblastoma." (PMID 37642765, 2023). "Glioblastoma cells have been reported to have high Cav-1 expression in association with EGFR-vIII (mut)." (PMID 34490102, 2021). "Polymerase I and transcript release factor (PTRF, cavin-1), which is a component of caveolae along with CAV1, is associated with chemoresistance in glioblastoma." (PMID 26646320, 2016). "Similarly, miR-1238 was significantly enriched in the serum of glioblastoma patients compared to healthy individuals, and loss of miR-238 may lead to the formation of drug-resistant glioblastoma via the CAV1/EGFR pathway." (PMID 33313406, 2020). "For example, exosomes under hypoxic conditions in highly malignant glioblastoma multiforme (GBM) brain tumours show an increase in matrix metalloproteinases, IL-8, PDGFs, and caveolin 1, some of which are already associated with a poor prognosis." (PMID 28350871, 2017). "In contrast, IDH1-mutant glioblastomas exhibit lower Cav-1 expression, reduced histone acetylation and decreased acetyl-CoA levels." (PMID 40243482, 2025). "Kagawa and colleagues have demonstrated that fatty acid-binding protein 7 (FABP7) is highly expressed in the nuclei of Isocitrate dehydrogenase 1 (IDH1) wild-type glioblastoma and promotes tumor proliferation by upregulating Cav-1 expression." (PMID 40243482, 2025). "Cav-1 is a key biomarker and potential therapeutic target in glioblastoma, as its high expression correlates with tumor aggressiveness and poor patient outcomes." (PMID 40243482, 2025). "A recent analysis of clinical datasets revealed a strong correlation between high Cav-1 levels and poor prognosis, particularly in the proneural and mesenchymal glioblastoma subtypes." (PMID 40243482, 2025). "Immunohistochemical analysis revealed that Cav-1 expression was predominantly detected in high-grade mixed oligoastrocytomas and glioblastomas with an oligodendroglial component, whereas low-grade tumors exhibited minimal expression." (PMID 40243482, 2025). "Serum Cav1 after RT in glioblastoma patients was insignificantly higher than in meningioma patients (p3 = 0.557)." (PMID 36121548, 2022). "In glioblastoma patients pre-RT, mean ± SD of serum Cav1 was 8.07 ± 1.69 that was increased to 9.16 ± 2.45 post-RT, while it was 7.29 ± 0.93 in healthy controls." (PMID 36121548, 2022). "Serum Cav1 showed a significant increase in glioblastoma subgroup after RT in comparison to healthy volunteers (p1 < 0.001)." (PMID 36121548, 2022). "For example, miR-1238 was reported to play a vital role in the treatment of glioblastoma as the fact that miR-1238 mediated the chemoresistance of glioblastoma and CAV1/EGFR was revealed to be the direct target during its functioning." (PMID 34606414, 2021). "Coherently with this, caveolin-1 is enriched in sEVs derived from glioblastoma cell lines under hypoxic conditions." (PMID 33302515, 2020). "Knockdown in resistant glioblastoma cells significantly reduces expression of both caveolin-1 and P-gp, while increasing the effectiveness of various cancer drugs." (PMID 27203393, 2017). "We previously reported that depletion of Cav1 significantly modified the expression of integrins in glioblastoma." (PMID 26474461, 2015). "As shown in glioblastoma, depletion of Cav1 in HNSCC enhanced α5β1 integrin expression endowing cells with an aggressive phenotype." (PMID 26474461, 2015). "We previously reported that stronger adhesion, motility and invasiveness can be observed in glioblastoma expressing high levels of α5β1 integrins induced by the disappearance of Cav1 from cells." (PMID 26474461, 2015). "Both pathways were shown to be activated in glioblastoma and in human peritoneal cells following Cav1 silencing." (PMID 26474461, 2015).
glioblastoma (continued). "CAV1, a principal structural protein of caveolae, was found to be an important contributor to the tumorigenicity of glioblastoma cells, and also could serve as an independent prognostic marker in glioblastoma." (PMID 40607003, 2025). "It was shown that high exosome-transferred miR-1238 level in TMZ-resistant glioblastoma cells could confer TMZ resistance by directly targeting the CAV1/EGFR pathway." (PMID 38379858, 2024). "Caveolin-1 showed a significant increase in glioblastoma subgroup after RT comparing to before RT." (PMID 36121548, 2022). "Moreover, cell invasion and expression of the matrix metalloproteinase genes MMP1 and MMP2 are significantly enhanced by CAV1 in glioblastoma cells." (PMID 29340103, 2017). "We could further show that α-CAIX and Ctx-B co-localized in caveolin-1 positive structures in WT-CAIX cells, and that CAIX co-localized with caveolin-1 in glioblastoma tumors." (PMID 28978009, 2017). "Silencing Cav1 in glioblastoma endowed cells mobility and invasion mediated by α5β1 integrins." (PMID 26474461, 2015). "As was reported that overexpressed caveolin-1 could reduce the aggressiveness of human glioblastoma U87MG cells, the expression of IL-8 was also greatly upregulated." (PMID 24379889, 2013). "CAV1 encodes Caveolin1, a negative regulator of EGFR activation, which acts as a tumor suppressor gene in glioblastoma (GBM) cells." (PMID 33407894, 2021). "Specifically, FABP7 enhances caveolae/caveosome formation by inducing histone acetylation at the Cav-1 promoter, but only in IDH1 wild-type glioblastomas." (PMID 40243482, 2025). "Fenretinide, a synthetic derivative of retinoic acid, led to the down-regulation of caveolin-1 expression at the protein level in MG-63 and HOS osteosarcoma and A-172,LI,CRS-A2 glioblastoma cells, decreasing tumor aggressiveness and restoring chemosensitivity." (PMID 34590611, 2021). "EVs released from glioblastoma (GBM) cells during hypoxia have been shown to be enriched in hypoxia regulated proteins and mRNA including caveolin 1 (CAV1), interleukin-8 (IL8), platelet-derived growth factor (PDGF) and MMPs." (PMID 30682793, 2019). "We found that CAV1 is 2-fold downregulated in the PAX6 KO cells compared to WT, which fit with observations in other glioblastoma cell lines where lower expression of CAV1 equals increased proliferation." (PMID 29716531, 2018). "For glioblastoma IGFBP2, EGFR_pY1068, HER2_pY1248, Caveolin-1, Akt_pT308, Fibronectin, Collagen_VI, and EGFR_pY1173 are decreased in the group of mutated cases." (PMID 30442178, 2018). "We investigated the effect of caveolin-1 (Cav-1) on the cholesterol efflux by apoA-I in HIV infected primary and THP-1 cell-differentiated macrophages as well as astrocyte derived glioblastoma U87 cells." (PMID 23067370, 2012). "In this study, we investigate the effect of Cav-1 on the cholesterol efflux in HIV infected macrophages and human astrocytes-derived glioblastoma U87 cells." (PMID 23067370, 2012). "Caveolin-1 is also among the proteins enriched in sEVs derived from EGFRvIII overexpressing glioblastoma cells, highlighting its role as a mediator of non-canonical EGFR signalling and as a stress survival mechanism." (PMID 33302515, 2020). "In glioblastoma (GBM), TRAF4 regulates caveolin 1 (CAV1) stability, and drives GBM cell stemness and temozolomide resistance by blocking ZNRF1-mediated ubiquitination and promoting USP7-mediated deubiquitination." (PMID 36765039, 2023).
metabolic syndrome (39 papers, 2009 to 2025). A cluster of metabolic risk factors for CARDIOVASCULAR DISEASES and TYPE 2 DIABETES MELLITUS. "In pediatric populations, Cav-1 gene polymorphisms have been associated with metabolic syndrome in obese children." (PMID 40358155, 2025). "Studies have shown that Caveolin gene polymorphisms (CAV-1) are involved in chronic diseases, such as metabolic syndrome." (PMID 38268038, 2024). "The presence of CAV-1 in individuals with metabolic syndrome, a disease linked to insulin resistance (IR), high blood glucose levels, hypertension, abnormal lipid levels, obesity, and increased WC, has been observed." (PMID 39104759, 2024). "The association of CAV-1 rs3807992 and metabolic syndrome has been confirmed through the effects of CAV-1 on visceral fat and IR." (PMID 38268038, 2024). "One study found that a Cav-1 genetic polymorphism interacted with polyunsaturated fatty acids to modulate metabolic syndrome risk." (PMID 37941054, 2023). "The loss of CAV1 in adipose tissue leads to an inability to store fat properly, leading to lipodystrophy, insulin resistance, hypertriglyceridemia, and metabolic syndrome." (PMID 37017811, 2023). "Previously, we demonstrated an association between the CAV1 rs1997623 C > A variant and metabolic syndrome (MetS)." (PMID 36497195, 2022). "The relationship of CAV1 variant and dyslipidemia is established by genome-wide association studies (GWAS) that exhibit a link of CAV1 gene proximal regions to low HDL-C level." (PMID 34001235, 2021). "In the CAV1 genotype, body fat distribution and dyslipidemia are suggested to be caused via the probable mechanism of disruption in insulin signaling." (PMID 34001235, 2021). "CAV1 knockout mice display numerous metabolic defects, including hyperglycemia, IR, and dyslipidemia, like those seen in humans with severe, nonsense CAV1 mutations." (PMID 34001235, 2021). "We investigated the potential interplay between IR levels and a selected human CAV1 gene variant (rs3807992) in modulating dyslipidemia and body fat composition." (PMID 34001235, 2021). "We examined the association between CAV1 and insulin signaling in modifying dyslipidemia and fat composition in overweight and obese women with a prevalent variant in the CAV1 gene." (PMID 34001235, 2021). "Today, various genome-wide studies have supported the correlation between the CAV1 variants and dyslipidemia, for instance, the low HDL and high TGs." (PMID 34544501, 2021). "The loss of CAV1 causes impairs glucose homeostasis and dyslipidemia, which is reversed by downstream aldosterone (MR) inhibition." (PMID 34955837, 2021). "In the present study, we show that the CAV1 rs1997623-A variant is significantly associated with metabolic syndrome, represented as a dichotomous trait (MetS) and as a quantitative trait of continuous metabolic syndrome score (siMS), in adult Arabs from Kuwait." (PMID 36338969, 2022). "Moreover, human studies on nonsense mutations show that severe CAV1 mutations exhibit IR and dyslipidemia." (PMID 34001235, 2021). "Interaction between the MIND diet and CAV1 rs3807992 gene variants on dyslipidemia is shown in." (PMID 34544501, 2021). "The present study indicates that using a novel diet as a MIND diet may help in improving dyslipidemia by providing a possible interaction with CAV1 rs3807992 gene variants." (PMID 34544501, 2021). "Allele and genotypic distribution of the CAV1 rs1997623 SNP based on metabolic syndrome risk score." (PMID 30622557, 2018). "Our previous studies demonstrated a potential association of CAV1 rs1997623 C/A variant with pediatric metabolic syndrome (MetS) in Arab children." (PMID 36338969, 2022). "In the present study, we aimed to investigate the potential association between the CAV1 rs1997623 C/A variant and metabolic syndrome (MetS) in Kuwaiti children." (PMID 30622557, 2018). "Components of MetS, including elevated glucose and dyslipidemia, inhibited autophagosome formation through CAV-1 activation." (PMID 39683397, 2024).
metabolic syndrome (continued). "Cav-1 has been extensively investigated in dyslipidemia, and numerous studies have revealed a potential correlation between Cav-1 genetic variations and the consumption of dietary fatty acids." (PMID 37941054, 2023). "Associated with metabolism pathways are DEGs related to metabolic syndromes like maturity-onset diabetes of the young 6 (NEUROD1), Sjogren-Larsson Syndrome (NXPH3), lipodystrophy (CAV1), and Rett Syndrome (GRID1)." (PMID 35883433, 2022). "Taken together, this study demonstrates that Cav-1 plays a critical role in endothelial stiffening induced by oxLDL in vitro and by dyslipidemia, disturbed flow and ageing in vivo." (PMID 36280774, 2022). "CAV1 has been widely studied in metabolic syndrome disorders such as dyslipidemia and CVD due to signal transduction, trafficking in cholesterol hemostasis, and triacylglycerol metabolism." (PMID 36338969, 2022). "In this regard, we have previously found insights about CAV-1 and insulin signaling in modifying dyslipidemia and fat composition in overweight and obese women." (PMID 34210318, 2021). "Characteristics of MetS including glucose and dyslipidemia inhibited the formation of autophagosomes via activating caveolin-1." (PMID 33937238, 2021). "Significantly increased CAV1 mRNA in the peripheral blood of patients with metabolic syndrome has been observed." (PMID 34955837, 2021). "Changes in CAV-1 rs11773845 and rs 926198 are related to high serum triglyceride (TG) levels, metabolic syndrome and WHR." (PMID 34753501, 2021). "Our results cast a new light on the IR mechanism and future studies will elucidate the clinical relevance of CAV1-IR in patients with dyslipidemia and high fat composition." (PMID 34001235, 2021). "Some experimental studies have reported that CAV-1 plays a substantial role in the development of dyslipidemia, hypertension, and atherosclerosis." (PMID 34210318, 2021). "Remarkably, there was a significant interaction between the MIND diet and CAV1 rs3807992 for dyslipidemia (β = − 0.25 ± 132, P = 0.05) in the crude model." (PMID 34544501, 2021). "AP-CAV-1 enhanced CAV-1 expression by ˃15%, inhibited CypA expression by ˃50% (P < 0.05) and significantly improved dyslipidemia, thus reducing neutral lipid peroxidation." (PMID 27124120, 2016). "Research has found that CAV-1 levels are increased in individuals with metabolic syndrome." (PMID 39104759, 2024). "Increased expression of CAV-1 is linked to the minor allele A, and reduced expression of CAV-1 can influence aldosterone and mineralocorticoid receptor signaling in various pathways connected to glycemia and dyslipidemia." (PMID 38268038, 2024). "Loss of CAV1 in adipocytes leads to impaired internalization and storage of lipids, lipodystrophy, hypertriglyceridemia, and metabolic syndrome but notably not to increased adiposity." (PMID 37017811, 2023). "It has been reported 20 that CAV1 expression is related to the clinical status of metabolic syndrome, and may become a potential target for the treatment and prevention of metabolic syndrome." (PMID 34234869, 2021). "CAV1 is the main part of caveolae and has been extensively studied in dyslipidemia and cardiovascular diseases for its important role in the signal transduction, interaction with steroid receptors, involvement in the activation of ion channels, and cholesterol hemostasis." (PMID 34384444, 2021). "In this regard, we revealed higher polyunsaturated fatty acid consumption might attenuate the CAV-1 rs3807992 associations with metabolic syndrome (MetS), and risk-allele appeared to have a higher risk of MetS, associated with higher saturated fatty acid consumption." (PMID 34210318, 2021). "Additionally, the studies have shown that CAV1 knockout mice display several metabolic abnormalities, including dyslipidemia, hyperglycemia and IR in liver and/or fat tissues." (PMID 32042299, 2020).